RNF4 (ring finger protein 4)
Diseases named in the same sentence as RNF4 in open-access papers (continued):
Sharing a sentence is not in itself a finding about the gene and the disease.
tumor (17 papers, 2005 to 2025). "We now report the use of a conditional-knockout Rnf4 mouse model to test the importance of Rnf4 for DNA repair, and to evaluate how Rnf4 deficiency contributes to tumor susceptibility." (PMID 38530355, 2024). "Rnf4 deficiency instead significantly delayed the rate of tumor formation in a mouse model of c-myc overexpression, indicating that Rnf4 contributes to the growth of incipient tumors." (PMID 38530355, 2024). "Finally, we tested whether Rnf4 deficiency causes accelerated tumor formation in Eμ-myc mice, a transgenic model for overexpression of the oncogene c-myc in B cells." (PMID 38530355, 2024). "As recently shown, the depletion of RNF4 in mice expressing the oncogene c-myc prolongs tumor-free survival, providing a compelling rationale for targeting RNF4 as an anticancer therapy." (PMID 41102521, 2025). "Our work further underscores the importance of SUMO regulation for tumor cell growth, and reveals the importance of RNF4 in this pathway." (PMID 38530355, 2024). "In contrast, mice expressing Eμ-myc with conditional deletion of Rnf4 in the B cell lineage showed a significant delay in tumor formation, with a median tumor-free survival of 215 days." (PMID 38530355, 2024). "Studies found that up-regulated RNF4 stabilizes certain oncoproteins and potentiates tumor cell properties." (PMID 35832191, 2022). "The SUMOylated oncoprotein is bound and ubiquitinated by RNF4 and is subsequently degraded, resulting in differentiation of the tumor cells." (PMID 34572023, 2021). "RNF4, a poly‐SUMO‐specific E3 ubiquitin ligase, is associated with protein degradation, DNA damage repair and tumour progression." (PMID 32722882, 2020). "The five TAAs identified (Tes, Rcn2, Rnf4, Cradd, Galnt3) are those whose expression is linearly related to the tumor mass increase in BALB-neuT mammary glands." (PMID 16351756, 2005). "In addition, nuclear p62 condensates interact with and stabilize PML-NBs, an established tumor suppressor, by sequestering and promoting degradation of RNF4, its Ub E3 ligase, which otherwise would have targeted PML for proteolysis." (PMID 41247240, 2025). "The rate of chromosome instability in untreated Rnf4Δ/Δ B cells is significantly higher than that in Brca1Δ11/Δ11 B cells, and yet no tumor susceptibility was observed in Rnf4-conditional-knockout mice." (PMID 38530355, 2024). "Although Rnf4–conditional-knockout B cells exhibited substantial genomic instability, Rnf4 deletion caused no increase in tumor susceptibility." (PMID 38530355, 2024). "However, future studies are required to fully elucidate the RNF4-dependent molecular axis in therapy-resistant tumors and to elucidate the full tumor spectrum where this axis acts as a pro-survival pathway." (PMID 36153321, 2022). "Importantly, all of the transcriptional and tumor-potentiating activities of RNF4 require both its ARM domain and binding to nucleosomes via a specific region at its C-terminus (NTR)." (PMID 29615551, 2018). "Overall, in all tumor portions of the tissue microarray (TMA) we observed higher levels of RNF4 and BMP6 compared to the non-tumor tissue." (PMID 36153321, 2022). "In APL RNF4 mediates the SUMO-dependent ubiquitination and subsequent degradation of the oncogenic driver PML-RARα, leading to differentiation of the tumor cells." (PMID 36153321, 2022). "The dependence of incipient tumor cells from Eμ-myc mice on RNF4 for survival and tumor outgrowth is an example of “non-oncogene addiction”." (PMID 38530355, 2024).
tumor (continued). "The mammalian SUMO-targeted E3 ubiquitin ligase Rnf4 has been reported to act as a regulator of DNA repair, but the importance of RNF4 as a tumor suppressor has not been tested." (PMID 38530355, 2024). "We identified 146 (13.6%) tumor-essential E3 ligases (mean of probabilities of essentiality across cell lines >0.563) in CRISPR screening, including two co-opted E3 ligases, VHL and RNF4." (PMID 37845222, 2023). "While technically, we were unsuccessful in performing immunohistochemistry of RGMb in these biopsies, these tumors were characterized by high levels of RNF4 and BMP6 compared with non-tumor tissue, as well as higher levels of the proliferation marker Ki67 (not shown)." (PMID 36153321, 2022). "In tumor cells, the ubiquitin ligase RNF4 ubiquitinates and stabilizes phospho-eIF2α but not ATF4 and CHOP, generating a positive feed-forward loop." (PMID 34106769, 2021). "Furthermore, we establish the ubiquitin E3 ligase BARD1, a tumor suppressor and partner of BRCA1, as an indirect RNF4 target, regulated by PIAS1." (PMID 29180619, 2017). "A challenge to evaluating the importance of RNF4 as a tumor suppressor is the lack of suitable animal models to test whether loss of RNF4 increases the risk of malignant cell growth." (PMID 38530355, 2024).
infection (5 papers, 2017 to 2023). The state of being infected such as from the introduction of a foreign agent such as serum, vaccine, antigenic substance or organism. "The BHRF1 cluster is selectively upregulated during productive infection and S3 Fig, suggesting that one or more of the encoded miRNAs may target RNF4." (PMID 28414785, 2017). "After two weeks, successful infection was demonstrated by green‐stained myocardia in the Scramble‐ and shRNF4‐treated groups, and endogenous RNF4 was reduced by 41% compared with that of the Scramble group." (PMID 32722882, 2020). "In accordance with the results above, at twelve‐week post‐infection, extensive interstitial fibrosis and disrupted intercalated disks were present in shRNF4 hearts, suggesting a specific effect of RNF4 on the heart." (PMID 32722882, 2020). "Here we discovered a novel function of the EBV miR-BHRF1-1 whereby, through inhibition of the SUMO-targeted ubiquitin ligase RNF4, the virus counteracts a cellular defense that operates during the late phase of productive infection." (PMID 28414785, 2017). "Sustained expression of the ectopic miRNA-resistant RNF4 during productive infection was accompanied by failure to accumulate high molecular weight SUMO2/3 conjugates." (PMID 28414785, 2017). "Thus, miR-BHRF1-1 promotes virus production by regulating a RNF4-mediated cellular defense against infection." (PMID 28414785, 2017). "The parallel accumulation of SUMOylated protein and decrease of RNF4 during productive infection is consistent with a scenario where the STUbL may regulate the abundance of SUMOylated viral proteins by promoting their proteasome-dependent degradation." (PMID 28414785, 2017). "The decrease of RNF4 is due to post-transcriptional downregulation by miR-BHRF1-1, a member of the BHRF1 microRNA cluster that is upregulated during productive infection." (PMID 28414785, 2017). "Later, it was shown that upon infection, E1B-55 K co-localizes with RING finger protein 4 (RNF4), a cellular SUMO-targeted E3 ubiquitin ligase, in specific insoluble aggregates in the nucleus, which mediates the interaction between Daxx and RNF4, leading to Daxx degradation." (PMID 37127643, 2023). "Our finding that the decrease of RNF4 is dependent on the activity of a viral microRNA illustrates a new strategy by which the virus interferes with SUMO-regulated events, and highlights a previously unrecognized function of EBV miRNAs during productive infection." (PMID 28414785, 2017).
heart disease (1 paper, 2020). "However, the role of RNF4 in heart disease has not yet been investigated." (PMID 32722882, 2020).
RNF4 also shares sentences with these, for which no sentence is quoted: neurodegenerative disease (2 papers); acute kidney injury (1); acute myeloid leukemia (1); adenoma (1); adult T-cell leukemia/lymphoma (1); breast adenocarcinoma (1); Cachexia (1); colon adenoma (1); heart failure (1); ischemia (1); leiomyosarcoma (1); liposarcoma (1); ovarian carcinoma (1); Retinal dystrophy (1); retinitis pigmentosa (1); systemic inflammatory response syndrome (1); testicular tumors (1).